LINC00567 (long independently transcribed non-coding RNA 567)
Gene: Long non-coding RNA gene on chromosome 13 (110,809,676 to 110,813,084, reverse strand). Ensembl gene ENSG00000259831.
Diseases named in the same sentence as LINC00567 in open-access papers:
LINC00567 is named in the same sentence as 2 diseases in open-access papers, as found by Europe PMC text mining. Sharing a sentence is not in itself a finding about the gene and the disease. The quoted sentences say what the papers report.
cancer (1 paper, 2021). A tumor composed of atypical neoplastic, often pleomorphic cells that invade other tissues. "To date, there have been no relevant studies on LINC00567, MTOR‐AS1, ZNF451‐AS1, or RPS6KA2‐AS1 in cancer." (PMID 33660438, 2021).
tumor (1 paper, 2021). "The experimental results of PCR showed that compared to normal samples, PRKG1‐AS1 and SH3BP5‐AS1 were significantly upregulated while LINC00567, LINC00996, MTOR‐AS1, RAB11B‐AS1, RPS6KA2‐AS1, and ZNF451‐AS1 were significantly downregulated in tumor tissues." (PMID 33660438, 2021). "In addition, LINC00567, LINC00996, MTOR‐AS1, RAB11B‐AS1, RPS6KA2‐AS1, and ZNF451‐AS1 were significantly downregulated in tumor samples compared with normal samples." (PMID 33660438, 2021).